KRAS (KRas proto-oncogene, GTPase)
Diseases named in the same sentence as KRAS in open-access papers (continued):
Sharing a sentence is not in itself a finding about the gene and the disease.
adenoma (continued). "In addition, the KRAS gene mutation status is one of the key differences between early stage and late-stage adenomas that are more likely to progress to invasive carcinoma." (PMID 39456841, 2024). "We next determined whether Fn infection was associated with BRAF mutation, KRAS mutations or MLH1 hypermethylation in adenomas/polyps." (PMID 37772997, 2023). "On the other hand, affinity of Fn to KRAS-mutated adenoma or carcinomas could be explained by KRAS mutated tissues’ requirement of a higher number of amino acids to survive and multiply in a nutrient-deficient environment." (PMID 37772997, 2023). "Next, a mutation in KRAS contributes to molecular pathogenesis by promoting adenoma formation." (PMID 36765950, 2023). "In our cohort, 9/27 of ADs showed KRAS mutation, predominantly in advanced adenomas." (PMID 36765865, 2023). "Colonoscopic findings (polyp size, number, site) and related histopathologic findings (adenoma, advanced adenoma, sessile serrated polyp) were analyzed in association with cancer clinicopathologic features and molecular data (mismatch repair status, KRAS, and BRAFV600E)." (PMID 37462969, 2023). "KRAS mutation in adenoma and carcinoma components and clinicopathologic features." (PMID 36083889, 2022). "BRAF and KRAS genes were mutually exclusive mutated, except for one advanced adenoma." (PMID 35761395, 2022). "Kirsten rat sarcoma viral oncogene homolog (KRAS) mutation follows, leading to larger adenomas." (PMID 35884381, 2022). "However, we did not confirm the relationship between the presence of a mutation in the KRAS gene in the index lesion and the risk of metachronous adenomas in this study." (PMID 35740488, 2022). "Three cases with a wild-type KRAS mutation in the adenoma component housed a KRAS mutation in the carcinoma component, and two cases with codon 12 mutation in the residual adenoma component demonstrated a wild-type KRAS mutation in the carcinoma component." (PMID 36083889, 2022). "Due to the discordance in the incidence of the KRAS mutation between the adenoma and carcinoma components, the adenoma component should be documented in the pathology report, and care should be taken not to include the adenoma component when collecting samples for molecular testing." (PMID 36083889, 2022). "It is, however, controversial whether adenoma formation can indeed be initiated by a mutation in KRAS." (PMID 35416770, 2022). "Therefore, the residual adenoma component should be recorded in pathology report and carefully excluded when collecting tissue samples for the KRAS mutation test." (PMID 36083889, 2022). "Similarly, our CRC cases' molecular analysis revealed that the serrated pathway harboring BRAF mutation accounted for a very small percentage (2.2%), which falls behind the adenoma-carcinoma KRAS-mutated pathway (45.2%)." (PMID 35619874, 2022). "KRAS is commonly mutated in a broad spectrum of benign and premalignant pathologies such as serrated lesions and adenomas that may arise at least in part due to the dispersal threshold being reached." (PMID 33895166, 2021). "Moreover, we found decreased LEF1 expression in the CMS3 and CRISA subtypes of CRC, which are characterized by KRAS mutations and in serrated adenomas, which typically harbor KRAS/Serine/Threonine-Protein Kinase B-Raf (BRAF) mutations." (PMID 34788095, 2021). "While variants in established cancer driver genes were identified in several of the present MSH3-deficient adenomas, each of the known more specific drivers of colorectal tumourigenesis (KRAS, FBWX7) was affected in only a single adenoma with the exception of APC." (PMID 34843512, 2021).
adenoma (continued). "Regarding CMS categorization, although no study has been reported in interval CRC, a higher proportion of screen-detected cancers could be hypothesized to be CSM2 and CMS3 because the tumors have an adenoma-carcinoma 10-year interval and KRAS mutations." (PMID 33809520, 2021). "However, these three genes also harbored some adenoma-private mutations; KRAS was mutated in the adenomatous regions of AC14 (p.G12D), AC30 (p.G12D), and AC39 (p.G12A) but not in their matched carcinoma." (PMID 32895052, 2020). "Similarly, heterogeneity was identified in case H154, where two spatially separated adenoma regions were sequenced and again two distinct KRAS mutations were detected (c.34G>T/p.G12V and c.38G>A/p.G13D)." (PMID 30166531, 2018). "Therefore, following APC loss, CtBP1 contributes to adenoma initiation as a first step, whereas KRAS activation and β-catenin nuclear localization promote adenoma progression to carcinomas as a second step." (PMID 29652830, 2018). "In fact, KRAS was mutated in 27% of adenomas while only 5% showed a BRAF mutation." (PMID 27902488, 2017). "The main finding of this study was that patients with at least one polyp that harboured a KRAS mutation were at higher risk of developing advanced polyps, specifically, advanced adenomas, compared to patients with polyps that harboured BRAF mutations or no mutation." (PMID 28953955, 2017). "Moreover, the KRAS mutation was an independent predictor of the development of advanced polyps and advanced adenomas, and it was a stronger predictor than other characteristics, like the size or number of lesions at baseline." (PMID 28953955, 2017). "On the other hand, KRAS mutations were found in 11.6% of adenomas and 20.9% of serrated lesions." (PMID 28953955, 2017). "Moreover, KRAS mutations were specifically associated with the development of metachronous advanced adenomas (OR: 2.23, 95% CI: 1.02–4.85)." (PMID 28953955, 2017). "KRAS mutation has been frequently detected in adenoma and cancer in FAP patients." (PMID 27563825, 2016). "KRAS mutations may, in part, drive the histologic progression of adenomas toward a villous histology and higher grades of dysplasia." (PMID 26910894, 2016). "The first pathway is a traditional adenoma-carcinoma sequence involving KRAS mutations." (PMID 26910894, 2016). "KRAS mutation was rare in superficial-type adenoma and adenocarcinoma." (PMID 26738600, 2016). "Methylation levels did not significantly increase from adenoma to cancer either, suggesting that methylation accumulation to form intermediate-methylation epigenotype and KRAS mutation was mostly completed by the adenoma stage, which resembles sporadic colorectal tumors." (PMID 27563825, 2016). "One of the most plausible hypotheses for such high concordance rate in the mutational status is that KRAS mutations are the early driving events in CRC progression from adenoma." (PMID 25090459, 2014). "We found KRAS mutations in 4/48 (8%) normal mucosa, 10/57 (18%) adenomas, and 32/80 (40%) CRCs." (PMID 23509688, 2013).
adenoma (continued). "KRAS mutations have previously been reported to be less frequent in depressed (0-IIc) lesions compared to other flat subtypes and or polypoid lesions which is consistent with the current study, where non of the four IIc adenomas showed a KRAS mutation." (PMID 22848674, 2012). "Either BRAF or KRAS mutation was observed in 82.4% of serrated adenomas (P < 0.001)." (PMID 21457162, 2011). "Overall, KRAS mutation occurred in 26.5% of adenomas while BRAF mutation was detected in only 4.8%." (PMID 16879389, 2006). "Of the 14 PNs with KRAS mutations in this series, 11 (79%) were adenomas." (PMID 16404419, 2006). "Since APC and KRAS are the most frequently mutated driver genes in the adenoma-to-carcinoma sequence, they could be expected to demonstrate alterations more frequently; moreover, the MUC6 and MUC3A mutations were the most frequent, followed by KRAS mutations, principally in TAs and VAs/TVAs." (PMID 40002249, 2025). "Finally, with respect to the clinical utility of our findings, it is possible that, as an adenoma acquires more mutations and progresses to carcinoma, the unique sensitivity of KRAS G12V cells to ACSS2 inhibition may diminish." (PMID 40131933, 2025). "Thus, presence of Fn may be advantageous for survival and growth of KRAS-mutated adenoma and/or carcinoma." (PMID 37772997, 2023). "Incident cancer may represent a distinct early event, in which MMR-D commonly precedes APC mutations and the endoscopic removal of precursor lesions during surveillance may be more effective in preventing KRAS-mutated lesions, since KRAS mutations are associated with conventional adenomas." (PMID 37568596, 2023). "CRC with the BRAF and KRAS mutations, derived from the serrated or conventional adenoma-to-carcinoma pathways (discussed further in detail later), are also represented by distinct epigenetic subtypes that may represent basic differences in transcriptional programs involved in these cancers." (PMID 35975243, 2022). "On the other hand, it has been suggested that an initial KRAS mutation might be able to drive the initiation of colorectal carcinogenesis, based on mutation frequencies in aberrant crypt foci and adenomas." (PMID 35416770, 2022). "However, heterogeneity has been described in adenomas, which might affect KRAS mutation detection suggesting that this oncogene might be subclonal and therefore inadequate for targeted cfDNA testing." (PMID 32380676, 2020). "Perhaps sampling of carcinomas has so far been too limited to identify heterogeneous KRAS mutations in relatively small clones, or, alternatively, during the progression from adenomas to carcinoma a clonal sweeping event might establish a founder KRAS mutant clone." (PMID 30166531, 2018). "Red meat intake was identified by the WCRF as a probable risk factor for CRC, and MPE research supports that this may especially be true for tumors of the traditional adenoma-carcinoma pathway; dietary heme intake shows stronger associations with KRAS.mutated tumors than KRAS wildtype tumors." (PMID 29249914, 2017). "The mouse colon epithelial KRAS-mutant isogenic cell line system replicates the early stage of the “classic” adenoma-carcinoma sequence, which is responsible for approximately 80% of CRC cases." (PMID 40131933, 2025). "This suggests that KRAS confers an evolutionary advantage that overcomes the necessity for polyclonality and results in the selection of a single dominant clone that drives adenomas progression." (PMID 40451939, 2025).
adenoma (continued). "CRC and adenoma patients were comparable in terms of age, sex, BMI, smoking status, APC and KRAS mutational status." (PMID 39980011, 2025). "In contrast to the conventional adenoma–carcinoma pathway, the serrated pathway primarily involves two mechanisms: BRAF/KRAS mutations and CpG island methylator phenotype (CIMP)." (PMID 38515581, 2024). "For 21 adenomas with both WES and WTS data, the latter was used to confirm the APC, PIGA, and KRAS mutations identified by WES, with concordant findings in all cases." (PMID 38546397, 2024). "A recent study of CRC has identified the APC oncogene to contain the highest number of pks motifs, whilst the KRAS gene, also characteristic of the conventional adenoma-carcinoma pathway and CMS3 subtypes, contained the fourth highest number of pks motifs." (PMID 39340753, 2024). "The oncogene BRAF, commonly associated with SSAs, was found in four patients (including three TVAs and one TA) and was exclusively comutated with KRAS, corroborating previous findings on conventional adenomas." (PMID 39554798, 2024). "The mouse colon epithelial KRAS mutant isogenic cell line system replicates the early stage of the “classic” adenoma-carcinoma sequence responsible for about 80% of CRC cases." (PMID 38464238, 2024).
adenoma (continued). "The sensitivity and specificity of fecal DNA multi-target testing, including KRAS mutation, BMP3, and NDRG4 methylation, for CRC and advanced adenoma was 80%, 91.2%, and the corresponding area under the curve was 0.856." (PMID 36905607, 2023). "In the group of genes (1069) found to be mutated both in adenoma and carcinoma samples, the most frequently mutated genes were APC (AD: 17/27, CRC: 33/51 (0.647)) and KRAS (AD: 8/27, CRC: 21/51 (0.412))." (PMID 36765865, 2023). "The most common initiating mutations of the adenoma to carcinoma sequence, APC and KRAS, increase proliferation, protein translation, and stemness." (PMID 37643866, 2023). "Mild upregulation of G2M and Myc target pathways was also observed in adenoma, but KRAS signaling and TNF-alpha signaling were downregulated, in contrast to carcinoma (p < 0.003)." (PMID 37121965, 2023). "In the mouse lung model of KRAS G12D-driven adenoma, it was found that coactivation of MYC would induce highly proliferative and invasive adenocarcinoma characterized by angiogenic and immunosuppressive stroma." (PMID 36185621, 2022). "Instead, mutations in KRAS, or more commonly BRAF, activate the RAS–RAF–MEK–ERK–MAPK axis as these are the earliest mutations observed in sessile serrated adenomas and its precursor hyperplastic polyps." (PMID 35975243, 2022). "The adenoma from the index of FAP104 showed a truncating APC variant (c.4666dupA, p.Thr1556fs; variant allele frequency (VAF) 23%) and KRAS c." (PMID 36387175, 2022).